PARP1 (poly(ADP-ribose) polymerase 1)
Diseases named in the same sentence as PARP1 in open-access papers (continued):
Sharing a sentence is not in itself a finding about the gene and the disease.
cancer (continued). "As noted by others, necrosis in acid conditions appears to be dependent on PARP-1 activation in cancer cells." (PMID 28884134, 2017). "Thereinto, olaparib (AZD2281, trade name: Lynparza, given orally), the first single drug for PARP1-mediated carcinoma therapy, clinically showed great inhibition ability against BRCA-mutation carcinomas." (PMID 28991194, 2017). "BRCA-mutant carcinomas, which are homologous recombination (HR) deficient and rely on PARP1-BER for survival, are highly sensitive to PARP1 inhibitors." (PMID 28991194, 2017). "This is a good supporting instance for the theory that PARP1 inhibition is also effective in DNA repair proficient carcinomas." (PMID 28991194, 2017). "Array data also demonstrates good tumoricidal efficiency of PARP1 inhibitors on these DNA repair defective carcinomas." (PMID 28991194, 2017). "PARP1 inhibitors, as used in monotherapy or maintenance therapy, have clinically presented promising efficiency against ovarian, breast, and other carcinomas." (PMID 28991194, 2017). "While this study was ongoing several laboratories showed that combining HDACis with specific PARP-1 inhibitors led to enhanced cell kill of cultured human cancer cell lines." (PMID 27196668, 2016). "Recently, PARP-1 inhibition has been demonstrated as an effective method for inducing synthetic lethality in cancers that have defective homologous recombination repair (HRR) pathway, such as cancers with BRCA-1/2 mutation." (PMID 27304949, 2016). "To overcome that resistance and expand use of PARP1 inhibition to cancers with functional HRR, we developed an antisense strategy to render the majority of tumor cells in a population BRCA2-deficient." (PMID 26959114, 2016). "Overall, this study and future work with mouse models should help shed more light on the real potential of new combinational therapy in nanomedicine using ATO as a PARP-1 inhibitor with DNA-damaging drugs for treatment of multiple drug resistant cancers." (PMID 27484730, 2016). "Due to the predominant function of PARP1 in DNA repair, its inhibition appeared as the strategy of choice in various forms of cancer to potentialize the cytotoxic action of chemotherapy and radiotherapy or to selectively kill tumors with dysfunctional repair." (PMID 27579892, 2016). "As HIPK2 is a tumor suppressor and mediator of DNA damage-induced apoptosis, our results propose a new measure to improve the efficiency of genotoxic cancer therapies possibly by interfering with the PARP1 WGR-HIPK2 interaction." (PMID 27787517, 2016). "The inhibition of PARP1 in these cancers resulted in the accumulation of single strand breaks (SSB) leading to DSB and eventually cell death upon cellular replication." (PMID 27043631, 2016). "To examine the mechanism through which the reduction of HDAC3 activity takes place, we determined the protein levels of class I HDACs and PARP-1 in delphinidin-treated cancer cells using western blot analysis." (PMID 27462923, 2016). "Blocking DNA repair is an attractive strategy for sensitizing cancer cells to radio- and/or chemotherapy, and being at the initiating point of the DNA repair cascades, PARP1 is a valid target for these strategies." (PMID 26950694, 2016). "When subjected to suspension culture for 24 h, the TUNEL staining and the levels of cleaved caspase 3 and PARP1 were greater in aggregates of bulk cancer cells than in enriched TICs." (PMID 27306323, 2016). "Due to its critical role in the repair processes of DNA strand breaks, PARP1 became an important target for drug discovery in cancer therapeutics." (PMID 26950694, 2016). "Our imaging approach is based on the strongly elevated PARP1 expression in cancer tissue compared to its healthy surrounding host tissue, as it has been shown for a large number of tumor types." (PMID 26808835, 2016). "PARP1 is an attractive target for tumor detection because its increased expression in a large number of cancers." (PMID 26900125, 2016).
cancer (continued). "PARP1 is a desirable imaging target, because it is overexpressed in a wide variety of cancers, and its overexpression allows the differentiation of tumor cells from healthy surrounding and invaded tissues." (PMID 26808835, 2016). "Inhibition of PARP1 was applied to the treatment of cancer patients in conjunction with conventional therapy inducing DNA damage." (PMID 27643881, 2016). "If the statistical epistasis between PARP1 and MMP2 is related to cancer risk, there must be crosstalk or merging of the two pathways, incorporating disparate cancer traits." (PMID 27588484, 2016). "Our results demonstrated that ZINC67913374 has promising potential as a PARP1 inhibitor for cancer drug development." (PMID 26907257, 2016). "The FDA approval of olaparib and other on-going PARP1 inhibition related clinical trials validates synthetic lethality as an effective therapeutic strategy in cancer drug development." (PMID 26907257, 2016). "The PARPi-FL in vivo imaging signal therefore reflects both the higher expression levels of PARP1 per nucleus as well as the higher nuclear density in malignant tumors." (PMID 26900125, 2016). "We have shown in models of cancer that PARPi-FL, a fluorescent PARP1-targeted small molecule, specifically binds to PARP1 with a similar affinity to Olaparib (Lynparza, Astra-Zeneca), an FDA-approved PARP1 inhibitor." (PMID 26900125, 2016). "The BRCA1-like vs. non-BRCA1-like signature was specifically enriched in high-grade (G3) cancers (90 % vs. 58 %, p = 0.0004) and was also frequent in tumors with strong (3+) nuclear PARP1 expression (37 % vs. 16 %; p = 0.087)." (PMID 27756336, 2016). "The LD plot indicated that there are multiple loci near rs8679 with high LD (r2 > 0.8), which suggests that fine mapping is necessary to evaluate the genetic effect of PARP-1 on cancer as well as functional studies." (PMID 27746584, 2016). "PARP1 inhibition in cancers defective in homologous recombination (HR) repair such as those containing mutations in BRCA1 or BRCA2, leads to effective killing through synthetic lethality." (PMID 26513298, 2015). "Dnmt1 modulates DNA methylation in cancer, and Parp1 is identified to localize within the Dnmt1 promoter by PARylation." (PMID 26184161, 2015). "Tan and his colleagues, for the first time, reported the immunogenic and autoantibodies to PARP1 in human sera and the presence of autoantibodies to PARP1were in the sera from cancer patients with Paraneoplastic Neurologic Syndrome." (PMID 25865228, 2015). "As a family of proteins PARPs have been shown to be druggable and PARP1 inhibitors are promising therapeutics for the treatment of cancer." (PMID 26091344, 2015). "During the writing of this paper we have become aware of a new study that looked at the effects of Parp-1 inhibition on radiation sensitivity in cancer cells." (PMID 26020242, 2015). "This suggests that PARP1 inhibition can inhibit NF-κB /IKK-mediated pro-survival signaling in cancer cells." (PMID 26540566, 2015). "Previous reports show that modulating DNA glycosylase expression, blocking abasic site repair, or inhibition of PARP1 offer alternative avenues for increasing sensitivity of cancer cells." (PMID 26090616, 2015). "Inhibition of Poly(ADP-ribose) Polymerase1 (PARP1) impairs DNA damage repair, and early generation PARP1/2 inhibitors (olaparib, niraparib, etc.)have demonstrated clinical proof of concept for cancer treatment." (PMID 26513298, 2015). "PAR level is quite high in our untreated cells probably because of the higher rate of basal PARP-1 activity, often observed in cancer cells." (PMID 25938539, 2015). "PARP1 inhibitorsare promising antitumor agents, since they act as chemo- and radiosensitizersin the conventional therapy of malignant tumors." (PMID 26483957, 2015). "In this review, the biological significance of Parp1 in transcription and the epigenetic modulation of Parp1 in pluripotent status, reprogramming process and cancer will be summarized." (PMID 26184161, 2015).
cancer (continued). "Several PARP-1 inhibitors have been explored to cancer therapy either alone or in combination with radiotherapy or other DNA-damaging drugs." (PMID 25749521, 2015). "By proteomic analysis, Parp1 is identified as a TCF4-associated protein and is essential for TCF4 downstream gene activation for proliferation in cancer cells." (PMID 26184161, 2015). "After the incubation, the impact of etoposide on macrophage polarization was studied and cancer cell apoptosis was assessed by western-blot for cleaved caspase-3 and cleaved PARP-1 protein, caspase activity assay and FACS analysis of Annexin V and PI staining." (PMID 26253167, 2015). "Mutation of TP53BP1 for instance, reverses the HR defect in BRCA1 mutant cancers and render these cancers resistant to PARP1 inhibition." (PMID 25852742, 2015). "MacroH2A1.1 is also a target for PARP1, which in turn is a common target for cancer drug development, because of PARP-1’s involvement in many cellular activities including DNA repair and transcription factor regulation." (PMID 26262644, 2015). "Personalized medicine uses targeted therapies on specific patients cohorts and PARP1 inhibitors represent a new promising class of chemotherapeutic drugs adopted to exclusively disrupt PARP1 function in HR-defective cancers." (PMID 25954303, 2015). "Further exploration of the specific PARP1-mediated DNA repair mechanisms regulated by miR-124 is needed to develop miR-124 as a cancer therapy." (PMID 26115122, 2015). "When the sera from cancer patients were tested for the presence of autoantibodies to PARP1 and BRCA1/BRCA2, the autoantibody responses slightly decreased and the positive autoantibody reactions varied from 0% to 50.0%." (PMID 25865228, 2015). "In this paper, we will discuss the mechanism involved in Parp1-driven pluripotency, cell reprogramming, and cancer." (PMID 26184161, 2015). "Over the past few years, a number of small molecule inhibitors of PARP1 have been developed for the treatment of cancer." (PMID 25883215, 2015). "In general, any query on cancer datasets (including Cbioportal for TCGA) would show PARP1 overexpressed in a considerable proportion of tumours." (PMID 26427375, 2015). "The use of β-lap with NAMPT inhibitors results in synergistic NQO1- and PARP1-dependent cancer cell death, allowing the use of lower doses and shorter treatment times for both therapeutics." (PMID 25590809, 2015). "A burst of poly(ADP-ribose) synthesis initiates DNA damage response, whereas PARP-1 inhibition kills BRCA-deficient tumor cells selectively, providing the first anti-cancer therapy based on synthetic lethality." (PMID 26626479, 2015). "On the other hand, PARP1-mediated processes play a role in oncogenesis, cancer progression, and therapeutic resistance." (PMID 26115122, 2015). "Since aberrant changes in DNA methylation have been widely reported in cancer, our data on PARP1’s involvement in DNA methylation provides a platform to further elucidate its effect in gene regulation both in normal and in disease states." (PMID 26305327, 2015). "Various PARP1 inhibitors, some of which are in clinical trials, are being developed for treatment of different cancer types." (PMID 26115122, 2015). "Currently, there is no literature to our knowledge that demonstrates FOXO3 is required for the caspase-3-mediated cleavage of PARP1 and caspase-3 proteins and for auranofin-induced apoptotic signaling in cancer cells." (PMID 25096914, 2014). "As PARP-1 protein contains a DNA-binding domain, which can bind to DNA strand breaks and repair the damaged DNA over a low basal level, the inhibitors of poly(ADP-ribose) polymerase 1 (PARP-1) have been indicated as the agents treated for cancer." (PMID 24876881, 2014). "Regarding the anatomical location of APE1, OGG1 and PARP-1, a decrease in gene expression was observed among patients with cancer in the rectum." (PMID 25268610, 2014).
cancer (continued). "By obstructing its interaction with DNA molecules, MGBLs block PARP-1 activity in vitro and in vivo, as we demonstrate using Drosophila, as well as human cancer-derived cells." (PMID 24504413, 2014). "The successful use of a PARP1 inhibitor for the treatment of tumor cells in which BRCA1 or BRCA2 is inactivated has provided a paradigm for the therapeutic exploitation of cancer cell addiction to a specific DNA repair pathway." (PMID 24618719, 2014). "The more lipophilic Hoechst33342 exhibits significantly higher cell permeability than Hoechst33258 and possesses proapoptotic effect on cancer cells, Therefore, we first tested Hoechst33342 to examine its ability to regulate PARP-1 functions in vitro." (PMID 24504413, 2014). "Regarding the anatomical location, for APE1, OGG1 and PARP-1, there was a decrease in gene expression among the patients with cancer in the rectum compared with the colon." (PMID 25268610, 2014). "They found SNPs (PARP1 rs8679 T>C and RAD51 rs7180135 A>G) associated with increased bladder and breast cancer risk and with improved cancer specific survival following radiation therapy in bladder cancer." (PMID 24616890, 2014). "Pooled analysis of the interaction effects between PARP1 Val762Ala and XRCC1 Arg399Gln on overall cancer risk." (PMID 24853559, 2014). "Taken together, our results identify the ERK1/2/PARP-1 axis as an additional potential therapeutic target for the preservation of lymphocyte function in cancer immunotherapy." (PMID 24586933, 2014). "ROS however also trigger poly(ADP-ribose) polymerase 1- (PARP-1) dependent cell death (parthanatos) in adjacent lymphocytes, which has been forwarded as a mechanism of immune escape in several forms of cancer." (PMID 24586933, 2014). "The joint effect between PARP-1 Val762Ala and XRCC1 Arg399Gln genotypes on the risk of cancer was addressed in the present study." (PMID 24853559, 2014). "The efficacy of MGBL action on PARP-1 in vitro and in vivo suggests that MGBLs can be a starting point for developing novel drugs against PARP-1 to treat malignant tumors sensitive to PARP-1 inhibition." (PMID 24504413, 2014). "As PARP-1 protein contains a DNA-binding domain, which can bind to DNA strand breaks and repair the damaged DNA over a low basal level, the inhibitors of poly(ADR-ribose) polymerase 1 (PARP-1) have been indicated as the agents treated for cancer." (PMID 24876881, 2014). "Different studies, in cancer models, suggest that PARP1 inhibition increases AKT phosphorylation, and its inhibition is necessary to reduce the capability of cancer cells to repair DNA damage and survive after insults." (PMID 23301673, 2013). "The nuclear enzyme PARP1 is a pleiotropic molecular sensor of DNA damage that exerts an important role in maintaining genomic integrity, so it represents a novel target in cancer therapy." (PMID 23301673, 2013). "Banking tumor biopsies from patients enrolled in PARP-1 clinical trials will greatly expedite the development of a panel of biomarkers, as will increased use of cancer genome sequencing and microarray technologies." (PMID 24350055, 2013). "In this study, we demonstrate that PARP-1 negatively controls the level of Ets-1 proteins in cancer cells via PARylation." (PMID 23405229, 2013). "Over 40 years of research invested from groups worldwide has advanced our understanding of poly(ADP-ribosyl)ation in cancer, identifying PARP-1 as a promising therapeutic target." (PMID 24392349, 2013). "Ets-1 expression was correlated with an increase in DNA damage when PARP-1 was inhibited, leading to cancer cell death." (PMID 23405229, 2013). "Recent reports have demonstrated that ETS fusion proteins, which are involved in many cancers, are drug-sensitivity biomarkers of PARP-1 inhibition." (PMID 23405229, 2013).
cancer (continued). "Regulating the activity of E-cadherin repressors represents a potentially beneficial strategy to fight cancer progression, and PARP-1 inhibitors accomplish this function by interfering with Snail1 activation." (PMID 23785295, 2013). "The most studied of these enzymes is poly(ADP-ribose) polymerase-1 (PARP-1), which is an excellent therapeutic target in cancer due to its pivotal role in the DNA damage response." (PMID 24350055, 2013). "Clinical trials which are now underway are examining the safety and efficacy of PARP-1 inhibitors as anti-cancers, including breast, uterine, and ovarian cancers." (PMID 23451039, 2013). "(vi) Stress survival response: finally, cancer cells respond to any therapy by elaborating various stress responses to survive; and PARP-1 and its product PAR play key roles in these stress responses." (PMID 24294592, 2013). "It will be of interest to explore more widely how PARP1 affects inducible gene expression under normal physiological circumstances and in disease situations such as cancer, where ERK pathway signalling is often deregulated." (PMID 24145797, 2013). "These and other related clinical discoveries have moved PARP-1 from interesting subjects of molecular analyses to the forefront as clinical targets for cancer treatment." (PMID 23451039, 2013). "Western blot analysis also demonstrated that TCN significantly induced the activation of caspase-8 and caspase-3, as well as the cleavage of PARP-1 in the four cancer cell lines." (PMID 23936501, 2013). "Since PARP-1 is a co-activator of NF-κB, the treatment with PARPi abrogates NF-κB-mediated transcription and kills these cancer cells." (PMID 23450678, 2013). "Over the past few years, PARP-1 has received a great amount of attention, due to the emergence of PARP-1 inhibitors as new therapeutics in cancer." (PMID 23405229, 2013). "TCN induces G0/G1 cell cycle arrest and apoptosis in cancer cells, activating pro-apoptotic proteins, including caspase-3, -8 and PARP-1, and decreasing the expression of anti-apoptotic proteins Bcl-2, Bcl-xL, and survivin." (PMID 23936501, 2013). "For this reason, inhibiting PARP activity, especially PARP-1, with small molecules reduces repair of ssDNA breaks, and is likely to be useful for treating cancers, stress, inflammatory responses and cardiovascular disease." (PMID 23451039, 2013). "Similar to PARP-1-mediated regulation of transcription factor activity, PARP-1 plays a role in regulating three of the sex hormone receptors most commonly linked to cancer: estrogen receptor (ER), progesterone receptor (PR), and androgen receptor (AR)." (PMID 24350055, 2013). "The critical role of PARP1 in DNA repair is reflected by its frequent upregulation in cancer, as well as the hypersensitivity of PARP1 null animals towards the mutagenic effects of DNA damaging agents." (PMID 24970148, 2012). "The inhibition of PARP1 was shown to sensitise these therapy-resistant cancer cell lines, and the effect was increased by the combination with a DNA ligase inhibitor." (PMID 24970153, 2012). "The deregulation of PARP1 is likely connected to its roles in different DNA repair processes as many cancer cells suffer from destabilised genome integrity." (PMID 24970153, 2012). "Based on the role of PARP1 at replication forks, a recent study showed a sensitisation of human cancer cells when the SMC1, SMC3 or RAD21 subunits of the cohesion complex were knocked down by siRNA in combination with PARP inhibition." (PMID 24970153, 2012). "Olaparib (AZD2281, AstraZeneca) is another PARP1 inhibitor that is being tested on various cancers, including breast." (PMID 22295252, 2012). "The important cellular role for PARP-1 is underscored by its critical role in inflammation and cancer." (PMID 23104860, 2012). "Many in vitro and in vivo experiments demonstrated that inhibition of PARP1 potentiates the cytotoxicity of anti-cancer drugs and ionizing radiation." (PMID 22480302, 2012).